TOP2A (DNA topoisomerase II alpha)
Diseases named in the same sentence as TOP2A in open-access papers (continued):
Sharing a sentence is not in itself a finding about the gene and the disease.
tumor (continued). "TOP2A and MCM2 immunostaining was localized to the nuclei of the tumor cells and benign mammary epithelium, while BUB1B protein immunostaining was cytoplasmic, as has been demonstrated in a variety of normal human tissues." (PMID 21785684, 2011). "In fact, a large subset of patients classified with very favorable outcome shared a common molecular tumor phenotype characterized by ER-positive and/or ERBB2-negative status and low proliferation (low levels of E2F1 as well as BIRC5,TYMS,TOP2A and TK1)." (PMID 17535433, 2007). "As TOP2A gene amplification is only found in HER2-amplified tumours, a sensible testing algorithm would be to test only HER2-amplified cases for TOP2A status." (PMID 17088909, 2006). "We performed FISH experiments to detect TOP2A amplification on all samples that were scored as HER2 1+, 2+ or 3+ by IHC and from which paraffin-embedded tumour material was available." (PMID 17088909, 2006). "Among the tumours with HER2 gene amplification, only 22% showed co-amplification of the TOP2A gene and 1% of the cases showed deletion of the TOP2A gene." (PMID 17088909, 2006). "An intriguing protocol-specified molecular correlative study found that, although all tumours had HER2 amplification, one third also had amplification of the topoisomerase ii&agr; (TOP2A) gene." (PMID 17576436, 2006). "TOP2A is highly expressed in both human and mouse TNBC tumor tissues and M6 cell lines." (PMID 40969744, 2025). "When specificially examining the tumor samples alone, we found that the cycling HepT population expressed high levels of EZH2, SUZ12, and EED, along with cell cycle regulators MKI67, AURKB, ASPM, TOP2A, and HELLS." (PMID 40766612, 2025). "In EC, TOP2A activity may be regulated by the WNT signaling pathway, impacting tumor cell proliferation and survival." (PMID 39910812, 2025). "TOP2A was mostly positive or moderately positive in tumours; it was not correlated with HB overall survival rates." (PMID 40099956, 2025). "Results showed that IFI27, KIF20A, KLK10 and TOP2A were significantly upregulated in tumor cells relative to normal cells, whereas SPINK7 showed no differential expression." (PMID 41008826, 2025). "In KIRC, genes like TOP2A, PTTG1, and others showed a negative link with tumor purity but a positive association with various immune cell types." (PMID 40390492, 2025). "Furthermore, Western blotting analysis of tumor tissues confirmed an upregulation of cleaved caspase-3, cleaved PARP, and γH2A.X proteins, accompanied by a downregulation of TOP2A protein expression in the treated groups relative to the control group." (PMID 41301416, 2025). "For example, gene module 9, containing the genes TOP2A and MCM4, correlated with resection/tumor grade and was mainly expressed by G1/S/G2/M tumor cells, providing support for the existing notion that higher-grade tumors contain larger proportions of proliferating malignant cells." (PMID 39880824, 2025). "Our data confirm previous reports of tumor cells resembling non-cycling GCPs (GLI2 + /TOP2A-), cycling GCPs (GLI2 + /TOP2A + ), and differentiated cells (NeuN + )." (PMID 38191555, 2024). "This study determined whether TOP2A modulates the canonical WNT signaling pathway to impact prognosis, metastatic tumor capability, and EMT occurrence in NSCLC." (PMID 38806610, 2024). "GPX4-driven ferroptosis specifically targeted the non-cycling tumor cell states, with upregulation of the canonical ferroptosis marker TfR solely in Top2a negative cells." (PMID 39192032, 2024). "Through the TCGA database, the expression levels of TOP2A were compared between more than twenty tumor tissues and their adjacent non-cancerous tissues, and the results showed that TOP2A was highly expressed in tumor tissues." (PMID 38593113, 2024).
tumor (continued). "To assess the effect of TOP2A on VM duct formation, we further examined TOP2A expression in 141 matched pairs of NSCLC specimens of tumor origin and adjacent non-tumor tissue origin by immunohistochemistry." (PMID 37407689, 2023). "Functionally, TOP2A could promote the Hippo-YAP signaling pathway, and was involved in tumor cell growth, bone-specific metastatic potential and tumor-induced osteolysis in LIHC." (PMID 37980167, 2023). "Particularly, They show high expression of cell proliferation-related genes MKI67 and TOP2A, but tumor stem cell marker genes CD44 and CD133 were not highly expressed." (PMID 37880655, 2023). "Genes such as MYBL2, TOP2A, and MMP1 were significantly upregulated in tumor tissues." (PMID 38124743, 2023). "Based on our results, MALAT1 upregulation in BC may function as a tumor promoter in BC via directly sponging miRNA 561-3p, and MALAT1 knockdown serves a vital antitumor role in BC cell progression through the miR-561-3p/TOP2A axis." (PMID 37244966, 2023). "Finally, our data also revealed that tumours expressing high BAZ2A levels also express high levels of KDM1A and TOP2A, suggesting common regulatory pathways." (PMID 37184661, 2023). "We not only confirmed that TOP2A knockdown inhibited LUAD, but it enhanced CPX anti-tumor effects." (PMID 35251970, 2022). "The expression of these ten target genes was significantly upregulated in the tumor tissues compared to the adjacent normal tissues, and three of them (PLK1, CDK1, TOP2A) were also marked as landmark genes in CMap, which means these genes were widely expressed across the lineage." (PMID 35326724, 2022). "With the exception of TOP2A and ERCC6L, which were upregulated in tumor samples." (PMID 36067196, 2022). "To validate the expression of ASMP, BUB1, CENPF, MAD2L1, NCAPG, SGO2, and TOP2A genes in tumor samples and adjoining nontumor samples, we measured their relative mRNA expressions using qPCR." (PMID 36072975, 2022). "In our study, we demonstrated that knocking down TOP2A inhibited HCC cell migration and invasion in vitro, and inhibited tumor growth and metastasis in vivo, downregulated E-cadherin and upregulated N-cadherin, Vimentin and Slug was observed in HCC cells overexpressing TOP2A." (PMID 35069905, 2022). "The correlation of tumor response and TOP2A expression was not statistically significant (p = 0.184)." (PMID 34638362, 2021). "Additionally, the TOP2A, RRM2, NEK2, CDK1, and CCNB1 proteins were overexpressed in tumor liver tissues as compared to normal liver tissues according to the Human Protein Atlas database and previous studies." (PMID 34681056, 2021). "Compared with other genes, MCM2, TOP2A, CDC45, KNTC1, RFC4 and RMI2 were highly expressed in CESC tumor tissues and might be better indicators of prognosis." (PMID 34174849, 2021). "At the end of tumor evolution, MKI67, TOP2A, and CDK1 genes began to express." (PMID 34397824, 2021). "Furthermore, for assessing the TOP2A role in HCC cell tumorigenicity, subcutaneous tumor formation experiments in nude mice were conducted." (PMID 34939898, 2021). "Blocking both TOP2A and TOP2B could, therefore, serve as a double-bolt lock to effectively inhibit tumor growth and progression." (PMID 34359577, 2021). "In summary, our study identified TOP2A, NCF4, FMNL1 and DOK3 as potential effective neoantigens for KIRC mRNA vaccine development, and patients with RIS2 tumor might benefit more from mRNA vaccination." (PMID 34872567, 2021). "From a biological standpoint, it does not make intuitive sense that patients with tumor TOP2A deletion would be more sensitive to anthracyclines." (PMID 34625570, 2021).
tumor (continued). "Although it remains speculative, patients with CNV in ERBB2 and CNV in TOP2A in the primary tumor and/or lymph node metastasis may benefit from HER2- or TOP2A-targeted therapy." (PMID 33298978, 2020). "For example, TOP2A displaying the most significant upregulation has been identified as a biomarker for HBV-related HCC and APOF with the most significant downregulation is considered a tumor suppressor in HCC." (PMID 33133125, 2020). "The production of truncated TOP2α isoforms can be determinants of drug resistance and/or play a role tumor cell biology not yet characterized." (PMID 32566920, 2020). "In addition, the co-expression analysis performed by Pearson correlation also suggest that expression of PRC1 and TOP2A had a strong correlation (r = 0.798, P < 0.0001) in both HBV-related HCC tumor tissue and adjacent normal tissue (r =0.565, P <0.0001)." (PMID 31737106, 2019). "Meanwhile, no significance TOP2A expression differences were found regarding to patients age, tumor location, size, stages or existing evasion to bronchial tubes and lymph nodes." (PMID 31528121, 2019). "We finally obtained a list of only five genes (AGXT; ALDOB; CYP2E1; IGFBP3; TOP2A) that were differentially expressed in tumor and nontumor tissues across studies, and were significantly correlated to HCC prognosis." (PMID 31771612, 2019). "Similar to the validation of survival analysis, ROC analysis of PRC1 (P < 0.001, AUC = 0.974, 95% CI = 0.958-0.990) and TOP2A (P < 0.001, AUC = 0.964, 95% CI = 0.944-0.985) in TCGA also performed well in distinguishing the HCC tumor and adjacent normal tissues." (PMID 31737106, 2019). "This implies that TOP2A expression is necessary but perhaps not sufficient for efficacious tumor cell killing by these agents." (PMID 29988316, 2018). "Interestingly, many of these genes are known to be involved in cell-cycle function (CDK2, CDK6, CCNB1, CEP55, CENPF), transcriptional regulation/tumor suppression (FOXO3, TOP2A), DNA-damage response (ASPM, XRCC4), and tumor progression (CYR61, MACC1, CXCR4)." (PMID 28482906, 2017). "The tumor samples of these patients were compared with the samples from non-treated patients for their respective Ki-67, TOP2A and RacGAP1 mRNA and protein levels as determined by means of the different evaluation methods." (PMID 27259241, 2016). "TOP2A protein overexpression was investigated in 40 pairs of tumor and matched nontumor tissues; TOP2A gene amplification was investigated in 22 pairs of the tissues which also used for HER2 gene amplification study." (PMID 25695068, 2015). "Within the ERPR+ group, 38 % of the tumor samples (5/13) yielded results representative of allelic instability of the HER2/TOP2A locus, whilst 62 % (8/13) did not." (PMID 26022247, 2015). "Proliferation rates did not change significantly with increasing passage of either clone suggesting that elevated levels of TOP2A do not affect tumor growth per se in culture." (PMID 26560244, 2015). "Select tumor samples were evaluated by ISH for MET TOP2A, and ALK, with no genetic aberrations (i.e. amplification or rearrangement) detected." (PMID 26498363, 2015). "By contrast, TOP2A overexpression was detected in 72.5% of tumor tissues but not detected in matched nontumor tissues." (PMID 25695068, 2015). "In contrast to post-mitotic cells such as cardiomyocytes, proliferating cells such as tumor cells express TOP2A or both isoforms rather than TOP2B alone." (PMID 25406834, 2014). "TOP2α levels peak at the G2/M phase and high levels of the same are expressed in proliferating tumor cells, whereas TOP2β levels do not significantly alter during cell cycle and is often present in both proliferating and differentiated cells." (PMID 25372714, 2014). "Although the anti-tumor effects of TOP2 poisons are usually attributed to TOP2A rather than TOP2B, the application of TOP2A level as a therapeutic predictor has been unsuccessful." (PMID 25406834, 2014).
tumor (continued). "In our series, the value of CA IX as a predictive marker of response to doxorubicin appears to be independent of HER2 and/or TOP2A amplification, suggesting a novel mechanism of anthracycline treatment resistance related to tumour hypoxia." (PMID 22333602, 2012). "Only one TOP2A amplified tumor exhibited a higher mRNA RQ value in comparison to non-amplified tumors." (PMID 22240029, 2012). "Mortality risk in smokers for gene expression differentiates current from never smokers in lung tumor and non-tumor tissue samples with TOP2A gene being one of them." (PMID 22952714, 2012). "Interestingly, whileKi-67 and TOP2A typically stained only a small fraction of tumor nuclei, E2F1 oftenstained the majority of tumor cells." (PMID 21629784, 2011). "Nuclear CDK1 and TOP2A was exclusively expressed in tumor tissues compared to normal tissues, including non-pulmonary normal organs." (PMID 21887332, 2011). "TOP2A over-expression seems to be correlating with the aggressiveness of HCC in terms of early age onset, advanced histological grading, microvascular invasion, chemoresistence, tumor recurrence and mortality." (PMID 20649994, 2010). "In total, TOP2A data are available from 194 HER2-positive and 19 HER2-negative tumours." (PMID 17088909, 2006). "There was no relative difference in recurrence-free or overall survival of TOP2A gene amplified vs non-amplified tumours depending on the arm of the study." (PMID 17088909, 2006). "This could indicate that TOP2A does not play as prominent a role in these specific tumor subtypes as initially hypothesized, or it may be regulated by alternative mechanisms not captured in this analysis." (PMID 40869426, 2025). "Additionally, H&E staining and immunohistochemistry of tumor tissues revealed disrupted tumor cell morphology, along with elevating the expression of cleaved caspase-3, γH2A.X, and TUNEL-positive cells, and decreasing the expression of TOP2A and the proliferation marker Ki67 in the treatment groups." (PMID 41301416, 2025). "Identification of Core Targets: Five critical anti-GC targets (CDK1, CCNA2, TOP2A, CHEK1, and PLK1) were identified, with a focus on their roles in cell cycle regulation and chemotherapy resistance, providing mechanistic insights into Diosgenin’s anti-tumor effects." (PMID 40487391, 2025). "Doxorubicin, as an anthracycline antibiotic, has an anti-tumor effect mainly through interfering with topoisomerase II (TOP2A) activity by interacting with DNA, but in recent years it has been found to bind to specific proteins and exert an anti-tumor effect through non-DNA targeting mechanisms." (PMID 41216288, 2025). "Notably, TOP2A and PRC1 were these 19 key prognostic genes, which were also identified as differential genes in the GSE40435 and GSE36895 datasets comparing paraneoplastic and tumor tissues." (PMID 40093809, 2025). "Finally, ATMi pre-treatment resulted in the attenuation of the CX-5461 response in both cell lines, suggesting that ATM-dependent signaling potentiates the tumor-killing mechanism of CX-5461 irrespective of the Top2α status." (PMID 39062087, 2024). "In the NeoTOP trial, the correlation between TOP2A gene amplification and protein level of expression will be further explored by immunohistochemistry using the Formalin-Fixed Paraffin-Embedded (FFPE) tumour tissue samples collected at different time points during the trial." (PMID 38453781, 2024).
tumor (continued). "In the ENTPD1/ITGAE double positive (tumor‐reactive, tr) population, local TCR clonal expansion and PD‐1 expression were used to classify the following four clusters of effector T cells (Teff): the TOP2A+ proliferating prTeff, IFNGhigh trTeff, IFNGlow trTeff, and IFNG−/CXCR6+ trTeff (trTeff‐CXCR6)." (PMID 38582099, 2024). "Downregulation of TOP2A may have the potential to turn the TOP2A-positive/HLA-I–negative phenotype into the HLA-ABC–positive/TOP2A-negative phenotype, which could promote the tumor immune response." (PMID 35784467, 2022). "Notably, tumor ECs were featured by upregulation of angiogenesis-related genes including collagens (e.g., COL4A1, COL4A2), PXDN, SPARC and HSPG2, as well as proliferation markers (e.g., MKI67, TOP2A)." (PMID 36138435, 2022). "In addition, expression inhibition of TMPO, TOP2A, RFC3, GINS1, and CKS2 genes could prevent tumor growth and TRIB3 expression suppression would be a favorable target for anti−angiogenic therapy." (PMID 34249670, 2021). "Furthermore, expression inhibition of TMPO, TOP2A, RFC3, GINS1, and CKS2 genes could prevent tumor growth." (PMID 34249670, 2021). "ERBB2 DNA and RNA (ICD and ECD) and TOP2α DNA and RNA status: (+ increased, = maintained and – decreased) considering the cut-off 2-fold and ERBB2 protein status following the 2013 ASCO/CAP guidelines (and maintained in the 2018 recommendations) of each of each tumor sample." (PMID 31301170, 2019). "The present analysis showed, for the first time, that the anti-tumor effect of fisetin was mediated mainly through modulation of multiple signaling pathways and via activation of CDKN1A, SEMA3E, GADD45B and GADD45A and down-regulation of TOP2A, KIF20A, CCNB2 and CCNB1 genes." (PMID 28052097, 2017). "Nevertheless we can confirm 6 of their identified genes (SPP1, TOP2A, AREG, EGR1, CD34, and IGF1) as well as one of the identified miRNAs (hsa-miR-101), that they found to be differentially expressed in lymph node metastases compared to primary tumours and to normal tissue." (PMID 26537449, 2015). "However, the results of TOP2A gene status are available only in 20 tumor tissues and 18 matched nontumor tissues." (PMID 25695068, 2015). "Also, we show for the first time that TOP2A gene copy number alterations are not observed in this type of tumor." (PMID 23398928, 2013). "Overexpression of miR-23a could not synergize 5-Fu-induced cytotoxicity and tumor inhibition, which indicates the mechanism of hypersensitivity induced by miR-23a is TOP2A poison-specific." (PMID 24103454, 2013). "It was recently observed that inhibition of TOP1 level could potentiate response of tumor cells to doxorubicin treatment without altering the expression level of TOP2A." (PMID 24103454, 2013). "No TOP2A deletions were detected in any of the 100 tumor specimens." (PMID 19061514, 2008). "Most of the tumours with amplification of TOP2A show neither expression of CK5/6 nor EGFR, only in two TOP2A-amplified samples expression of CK5/6 or EGFR could be detected." (PMID 17088909, 2006). "Although we could confirm that the TOP2A gene is amplified in a proportion of tumours harbouring an HER2 amplification, this abnormality does not appear to be responsible for the lack of efficacy of high-dose alkylating chemotherapy in this patient group." (PMID 17088909, 2006). "The tumor cell subsets stratified by three main types: First, tumor-dominant cell subsets (Tumor 1 and 2 clusters) lacking clear enrichment of other cell types, with Tumor 1 cluster characterized by greater expression of proliferation genes (e.g., Ccnd1, Top2a, Myc)." (PMID 40171265, 2025). "Notably, among the top-ranked CTD-suppressed genes, we found that five genes, including TOP2A, ACSL4, SQLE, CDK4, and SLC6A14 were significantly elevated in HCC clinical specimens, suggesting that NCTD targets to inhibit the expression of these genes to exert anti-tumor effects in HCC." (PMID 40271060, 2025).